IL2 (interleukin 2)
Diseases named in the same sentence as IL2 in open-access papers (continued):
Sharing a sentence is not in itself a finding about the gene and the disease.
Sepsis (continued). "Acquired coagulation abnormality of FVII has been associated with the use of anti-thymocyte globulin in aplastic anemia, as well as with penicillin, cephalosporins, interleukin-2, malignancies, and conditions such as sepsis, pancreatitis, and multiple myeloma." (PMID 40130099, 2025). "Disruption of IL-2/STAT5 signaling in sepsis contributes to lymphopenia and T cell exhaustion, reinforcing immunosuppressive conditions." (PMID 40699828, 2025). "The highest IL-2 concentrations were detected in the sepsis (G3) and saline-treated (G4) groups (p < 0.05)." (PMID 41517447, 2025). "Nevertheless, IL-2 levels were markedly higher in patients with sepsis on days +14 and +21, suggesting sepsis influences IL-2 expression, consistent with those in patients with aGVHD, without affecting result interpretation." (PMID 40718494, 2025). "In the early stages of sepsis, IL-2 enhances T cell proliferation and activation, promotes the immune response, and aids in clearing infections." (PMID 40166075, 2025). "Our results suggested IL-4 levels and the IL-2/IL-4 ratio on day +7 were higher in patients with sepsis than those in the control group; however, the difference was not significant." (PMID 40718494, 2025). "The detailed mechanism by which 9-Hydroxystearate reduces sepsis risk via FGF-19 and IL-2 requires further investigation." (PMID 39205680, 2024). "Among them, IL2 showed relatively good binding affinity to the core active ingredients, suggesting its crucial role in the treatment of sepsis with SMI, but further experimental validation is still needed." (PMID 39584444, 2024). "IL-2 acts as a pro-inflammatory cytokine, contributing to the pathogenesis of sepsis by participating in the systemic inflammatory response." (PMID 39205680, 2024). "IL-2 and IL-8 were significantly decreased in the blood of G. parasuis-challenged piglets, findings similar to those of a study of sepsis-induced immunosuppression." (PMID 39075562, 2024). "The results showed that sepsis patients exhibited significantly elevated levels of the inflammatory factor IL-2 and significantly reduced levels of FGF-19 and AXIN1 compared to healthy controls." (PMID 39205680, 2024). "CD28 agonism during sepsis also led to increased IL-2 production from bulk CD8+ T cells, driven mainly by CD44hiCD8+ T cells." (PMID 38633258, 2024). "In fact, a higher frequency of TCIRCM from CLP hosts produce IL-2 in response to Ag stimulation when examined 30 days post-sepsis." (PMID 36756117, 2023). "Significantly higher levels of serum IL-6 (404.54 ± 543.38 vs 185.11 ± 242.73 pg/ml), IL-2 (5.30 ± 2.03 vs 4.11 ± 1.67 pg/ml), and IL-4 (4.76 ± 1.31 vs 3.34 ± 1.37 pg/ml) were found in patients with KD combined with severe sepsis (all P<0.05, respectively)." (PMID 37234775, 2023). "Increased IL-2 production aligns with the enrichment of TCM in the TCIRCM pool at a late time post sepsis, as these cells have better IL-2 production than TEM." (PMID 36756117, 2023). "Another group showed thermal injury-plus-sepsis or sepsis alone in rats lead to a suppressed CD4+ T proliferation/IL-2 production and a substantial down-modulation of lymphocyte survival in mesenteric lymph nodes." (PMID 35251032, 2022). "further suggested that activation of the TGFBR2/Smad pathway was responsible for LPS-induced sepsis, resulting in increased levels of IL-2 and TNF-α and reduced overall survival of mice with sepsis." (PMID 35090386, 2022). "Three subjects died during this trial: one due to complications during surgical resection, one from sepsis during consolidation, and one from brain herniation due to complications attributed to IL‐2 and dinutuximab on day 44 of immunotherapy." (PMID 35355452, 2022). "IL-2 levels exhibited a similar trend, as evidenced by increased levels in the sepsis 24 h group but significantly decreased levels at 48 h after CLP." (PMID 34512319, 2021).
Sepsis (continued). "Antagonism of cerebral HMGB1 improved the proliferation and IL-2 release of T cells and reversed the polarization of Th2 cells in the sepsis 48 h group." (PMID 34512319, 2021). "When ONB/MPA treatment was employed in murine models of LPS- and CLP-induced sepsis, we observed significant downregulation of growth factors and cytokines (i.e., IL-2, IL-6, and TNF-α)." (PMID 32226527, 2020). "The results obtained showed that the rats in the untreated sepsis group showed significantly elevated levels of pro-inflammatory cytokines (IL-1α, IL-2, TNF-α, IL-6, IFN-γ, IL-1β) in plasma." (PMID 32076015, 2020). "Sepsis-related mediators, such as endotoxin and the pro-inflammatory cytokines IL-1β, IL-2, IL-6, TNF-α, and IFN-β, have been shown to induce high expression of iNOS." (PMID 33123008, 2020). "Its release in blood is an indirect marker of activation of T-cells which secrete IL-2 during sepsis." (PMID 31661804, 2019). "In order to evaluate the occurrence of sepsis-induced T-cell functional alterations in this cohort, we measured intracellular IL-2, TNFα, and IFNγ productions after ex vivo activation of T lymphocytes from patients and HVs." (PMID 30995946, 2019). "The administration of BoxA reversed the proliferative arrest of CD4+ T cells during the course of sepsis and was accompanied by the elevated expression of IL-2 (both protein and mRNA) when compared with the sepsis group." (PMID 30881224, 2019). "Our findings also demonstrate that CD43 drives a TH1 phenotype, as CD43-/- demonstrate significantly decreased IL-2+ CXCR3+ CD4+ (TH1-like) cells with a concomitant increase in IL-4+ CCR4+ CD4+ (TH2-like) cells in sepsis." (PMID 30226896, 2018). "In a previous study conducted by this research team, we found an increase in the level of PD-1-positive T cells and reduced IL-2 production, activation, and proliferation in elderly sepsis patients and older mouse sepsis models." (PMID 30349725, 2018). "This demonstrates a more significant reduction in IL-2 in the setting of alcohol sepsis than occurs due to either alcohol or sepsis alone." (PMID 27861506, 2016). "This demonstrates a more significant reduction in IL-2 in the setting of alcohol sepsis than is seen due to either alcohol or sepsis alone." (PMID 27861506, 2016). "The distribution of haplotype of the TGF-β, TNF-α, IL-2, IL-4, IL-6 and IL-10 genes were studied in patients with sepsis and non-sepsis." (PMID 26561011, 2015). "Compared with the control group, the inflammatory cytokine levels of IL-2, IL-6 and IL-10 in patients with sepsis or intracranial infection were significantly elevated (both P<0.05)." (PMID 24887408, 2014). "As analyzed above, CRP and the three cytokines IL-2, IL-6 and IL-10 were differentially related to sepsis and intracranial infection." (PMID 24887408, 2014). "In the ex vivo stimulation study, the percentage of CD25+ activated CD4+ T cells and the IL-2 concentration in the supernatants also significantly decreased in elderly patients with sepsis compared with adult patients with sepsis (P <0.05)." (PMID 24962182, 2014). "Usual maneuvers to treat patients with cytokine-induced systemic responses, such as sepsis, are managed very differently than HD IL-2 patients." (PMID 31546315, 2014). "Any documented gastrointestinal or central line infection or suspected sepsis is a criterion to stop IL2." (PMID 31546315, 2014). "• Aging and sepsis induces T-cell exhaustion with impaired activation, IL-2 production, and proliferation in patients and mice." (PMID 24962182, 2014). "This is the potential mechanism for counter regulation of IL-2 versus IL-10 during sepsis or intracranial infection." (PMID 24887408, 2014). "Compared to non-septic patients, septic patients tended to have persistently decreased intracellular production of IFN-γ and IL-2 at multiple time points during the course of their sepsis." (PMID 24387680, 2014).
Sepsis (continued). "Nor was there supernatant evidence that interphase neutrophils from sepsis patients produced cytokines (IL-2, IL-4, IL-6, IL-10, TNF or IFNγ) when cultured in vitro (unstimulated total cells or enriched CD66b + interphase neutrophils)." (PMID 25084831, 2014). "The IL-2 induced toxicity shares many features with sepsis such as capillary leakage, systemic complement activation, and a relatively non-specific rise in inflammatory mediators such as TNF-alpha, C-reactive protein, and in advanced cases organ failure." (PMID 24884532, 2014). "This syndrome was described after snake bites in patients with sepsis and in patients treated with interleukin-2 and taxotere." (PMID 24215543, 2013). "IL-2 protein levels were reduced in sepsis and bacteraemia compared to controls (P = 0.02) but similar in pneumonia and non-pneumonia groups." (PMID 21711552, 2011). "Median Pre-operative IL-2 mRNA copy numbers were similar to those of bacteraemic patients, less than healthy controls, and greater than patients with sepsis (Wilcoxon rank sum test P < 0.0001)." (PMID 21711552, 2011). "IL-2 gene expression was lower in the bacteraemia group compared with controls, and lower still in the sepsis group (P < 0.0001)." (PMID 21711552, 2011). "There was no relation between severity of organ failure and/or outcome in patients with sepsis and IL-2, IL-7, IL-15, Bim, Bax or Bcl-2 gene expression." (PMID 21711552, 2011). "Pre-operative IL-2 and IL-7 mRNA values of patients in the thoracic surgery study were compared with patients in the sepsis study." (PMID 21711552, 2011). "Dallal and coworkers demonstrated that T-cell suppression during neonatal sepsis is accompanied by a decrease in IL-2 production." (PMID 15566594, 2004). "This study aimed to investigate the effects of cetirizine and dexamethasone (alone and in combination) on serum levels of Maresin-1 (MaR-1), TNF-α, IFN-γ, IL-1, IL-2, IL-6, IL-8, and IL-10 in a rat model of sepsis induced by the cecal ligation and puncture (CLP) method." (PMID 41517447, 2025). "After activation with anti-CD3/CD28 antibodies, flow cytometry analysis showed that CD4+ T cells from sepsis patients produced significantly less interleukin-2 (IL-2) and interferon (IFN-γ), suggesting that these cells are functionally suppressed and exhausted." (PMID 41306770, 2025). "Similarly, in our study, IL-2 levels significantly increased (p < 0.01) in the sepsis groups compared to controls." (PMID 41517447, 2025). "Additionally, MMP9 induced increased PD-1 expression on CD4+ T cells and reduced IL-2 and IFN-γ production upon anti-CD3/CD28 stimulation, confirming the association between MMP9 and CD4+ T cell exhaustion during sepsis." (PMID 41306770, 2025). "Therefore, this study aimed to investigate the effects of cetirizine and dexamethasone (alone and in combination) on serum levels of MaR-1, TNF-α, IFN-γ, IL-1, IL-2, IL-6, IL-8, and IL-10 in a rat model of sepsis induced by CLP method." (PMID 41517447, 2025). "Additionally, 9-Hydroxystearate exhibited a dual protective role against sepsis, positively associated with FGF-19 and negatively with IL-2, contributing 9.436% and 12.565% respectively to its protective effect." (PMID 39205680, 2024). "Sphingomyelin (d18:2/24:2) was positively associated with sepsis and negatively associated with IL-2, but since IL-2 was positively associated with sepsis, it is unlikely to be a mediator." (PMID 39205680, 2024). "Study found that cytokines such as CCL2/MCP‐1, IL‐10, IL‐2, and TNF‐alpha were associated with lymphocyte morphology changes and other laboratory test results related to inflammation in sepsis, and those parameters were decreased in sepsis recovery." (PMID 39305165, 2024). "However, MDSCs isolated from sepsis exhibit immunosuppressive function by inhibiting T cells proliferation and IL-2 production only at or after 14 days following sepsis onset." (PMID 38609858, 2024).
Sepsis (continued). "We identified 36 metabolites significantly associated with sepsis (p < 0.05), with AXIN1, FGF-19, FGF-23, IL-4, and OSM showing an inverse association, suggesting a protective role, while IL-2 exhibited a positive correlation, indicating a potential risk factor." (PMID 39205680, 2024). "Similar negative associations were observed for AXIN1 (OR = 0.715, CI = 0.517–0.990), FGF-23 (OR = 0.783, CI = 0.624–0.981), IL-4 (OR = 0.772, CI = 0.608–0.980), and OSM (OR = 0.755, CI = 0.592–0.962), whereas IL-2 showed a positive correlation with sepsis (OR = 1.320, CI = 1.008–1.729)." (PMID 39205680, 2024). "When the efferocytically-licensed monocytes were subsequently challenged with a cocktail of LPS, IFN-γ, and IL-2 to simulate sepsis, we saw IL-10 increase in all samples, but only monocytes efferocytically-licensed with viable MSC significantly increased output of kynurenine." (PMID 37592321, 2023). "Stimulated splenocytes from septic JAM-A–/– mice had decreased frequency of TNF+CD4+ cells and elevated frequency of IL-2+CD4+ cells, both of which could alter antimicrobial response and potentially play a causative role in improved survival from sepsis." (PMID 35819838, 2022). "We speculate that EHBA may be affected by the environmental factors IL-2 and Lac to affect PD-1 expression on the surface of T cells, which in turn affects the 7-day prognosis of sepsis patients." (PMID 33868224, 2021). "In accordance with organ dysfunction in the FtHfl/fl mice, 24 h after CLP surgery, there was a significant increase in the levels of cytokines that have been implicated in the pathogenesis of sepsis, including the pro-inflammatory cytokines, TNF-α, IFN-γ, IL-6, IL-12, CXCL1, IL-1β, and IL-2." (PMID 30804939, 2019). "However, only MDSCs obtained at and beyond 14 days post-sepsis significantly suppressed T lymphocyte proliferation and IL-2 production." (PMID 31722736, 2019). "The administration of exogenous cytokines can have a marked effect on the number and function of various immune cell populations in sepsis survivors, as demonstrated by the preclinical and clinical data touting the benefits of IL-2, IL-7, IL-15, and Flt3L (among others)." (PMID 30379932, 2018). "Therefore, the efficacy of IL-2/α-IL-2 mAb complexes (IL-2c) therapy in reversing sepsis induced impairment of NK-cell-mediated MCMV control was explored next." (PMID 30379932, 2018). "Interleukin-2 is used both in the case of sepsis, where the role ofbacteria is obvious, and in the treatment of cancer, where the role of bacteriais less obvious but there may be a combination of bacterial tissue damage andthe underlying disease." (PMID 28740730, 2017). "Sepsis may also lead to CMV reactivation through the inability of interleukin-2 to restore natural killer cell function, which is important in controlling the virus after acute infection and reactivation." (PMID 28143418, 2017). "These initial IL-2 concentrations are greater than those reported in patients with sepsis." (PMID 27727279, 2016). "Cytokines such as interleukin-2, interferon-alpha, and interleukin-6 are hypothesized to be the main mediators for increased capillary leak in acute inflammatory states like sepsis." (PMID 26908009, 2016). "However, impaired T cell activation, IL-2 production, and proliferation were observed in elderly sepsis patients and aged mice at relatively early stages (24 h after diagnosis in humans and after CLP treatment in mice)." (PMID 24962182, 2014). "In this perspective, the attempt to treat peripheral mononuclear cells of sepsis patients ex vivo with IL-2 before re-injecting them is an interesting approach that prevents the delivery of this cytokine to the bloodstream, allowing it to act strictly on the desired cells." (PMID 24886820, 2014). "Interleukin-2 is a proinflammatory cytokine as interleukin-6, tumor necrosis factor-α, and interferon-γ, which participate in the inflammatory response regulation in sepsis." (PMID 22645477, 2012).
Sepsis (continued). "In cultured PBLs, IFN-γ gene expression was decreased in response to LPS and increased in response to CD3ab with sepsis: IL-7 gene expression increased in response to LPS in controls and to CD3ab with sepsis; Bcl-2 gene expression decreased in response to combined CD3ab and IL-2 with sepsis." (PMID 21711552, 2011). "We also investigated the effect of exogenous IL-2 on cytokine gene expression in cultured mononuclear cells to determine whether IL-2 might plausibly be considered as an immune adjuvant for patient with sepsis." (PMID 21711552, 2011). "The response rate to high dose IL-2 is low (16%) but durable cures have been observed in approximately 6–10% of the patients that can tolerate the systemic toxicity (i.e. hypotension, capillary leak syndrome, sepsis and renal failure)." (PMID 18334033, 2008). "The latest predictive model suggests that age, neutrophils, lymphocytes, IL-2, IL-10, and procalcitonin are the major variables in predicting progression to severe illness, particularly white blood cell count and procalcitonin inflammatory index, which are commonly used in clinics to judge sepsis." (PMID 38127118, 2024). "However, in this study, IL-2 and IL-4 levels were in normal range, so the increase in IL-6 may be a predictor of KD combined with severe sepsis." (PMID 37234775, 2023). "The importance of assessing suppressive MDSC cell activity early in sepsis may be further obviated by recent evidence demonstrating that only MDSCs that are obtained at >14 days post-sepsis significantly suppress T lymphocyte proliferation and IL-2 production." (PMID 36466851, 2022). "IL-2 and Lac, which were identified by Spearman correlation analysis, may play important roles in the expression of PD-1 on the surface of T cells and affect the prognosis of patients with sepsis." (PMID 33868224, 2021). "Furthermore, CD43-/-septic mice exhibited a prominent Th2 skewing following sepsis relative to WT septic mice, as evidenced by a significant decrease in the frequency of IL-2+ CXCR3+ TH1 cells as a significant increase in the frequency of IL-4+ CCR4+ TH2 cells." (PMID 30226896, 2018). "Thus, it is possible that increased CXCR4 expression during sepsis may amplify this pathway and result in enhanced IL-2, IL-4, and/or IL-10 secretion." (PMID 29232699, 2017). "IL-2 gene expression was lower in bacteraemia patients compared with controls, and lower still in patients with sepsis; IL-7 gene expression was similar in control and bacteraemic patients, but lower in patients with sepsis; IL-15 gene expression was similar in the three groups." (PMID 21711552, 2011). "At early stage of sepsis, referred to as systemic hyperinflammatory response syndrome (SIRS), cytokines including tumor necrosis factor α (TNF‐α), interleukin (IL)‐1, IL‐2, IL‐6, are significantly elevated, which results in aberrant STAT3 activation." (PMID 41042728, 2025). "It induced high levels of IgG, IgM, IL-2, and IFN-γ, as well as lymphocyte proliferation, resulting in significant effectiveness in preventing K. pneumoniae infection in a mouse sepsis model." (PMID 40266107, 2025). "In conclusion, a higher IL-2/IL-4 ratio on day +7 was an early predictor of aGVHD post-HSCT, even with sepsis or ES." (PMID 40718494, 2025). "The significant correlations observed between piperine and AXIN1, as well as 9-hydroxyoctadecanoic acid and IL-2 and FGF-19, further support the intricate relationships between metabolites and inflammatory factors in the context of sepsis." (PMID 39205680, 2024). "Experimental validation confirmed significantly elevated IL-2 levels and reduced FGF-19, AXIN1, piperine, and 9-hydroxyoctadecanoic acid levels in sepsis patients compared to healthy controls." (PMID 39205680, 2024).